GOLM1 (golgi membrane protein 1)
Description:
Unknown. Cellular response protein to viral infection.
Synonyms: C9orf155; GOLPH2; GP73; FLJ23608; bA379P1.3; HEL46; PSEC0257
Tractability: Antibody: its Gene Ontology location is reachable by antibodies, with high confidence; UniProt predicts a signal peptide or a membrane-spanning region. PROTAC: ubiquitination databases record sites on it; its protein half-life has been measured.
Gene: Protein-coding gene on chromosome 9 (86,026,138 to 86,100,173, reverse strand). Ensembl gene ENSG00000135052.
Subcellular location: Golgi apparatus, cis-Golgi network membrane
Subcellular location (Human Protein Atlas): Golgi apparatus
Pathways (Reactome):
Metabolism of proteins: Post-translational protein phosphorylation; Regulation of Insulin-like Growth Factor (IGF) transport and uptake by Insulin-like Growth Factor Binding Proteins (IGFBPs)
Gene Ontology:
Molecular function: protein binding
Cellular component: extracellular region; Golgi apparatus; endoplasmic reticulum lumen; plasma membrane
Genetic constraint (gnomAD): Loss-of-function variants: 25 observed, 39.46 expected, observed/expected ratio (o/e) 0.63, 90% interval 0.46 to 0.88. The upper end of that interval is the gene's LOEUF score, 0.88, which puts it in group 3 of 6, group 1 being the genes least tolerant of losing a copy. Missense variants: 372 observed, 393.05 expected, observed/expected ratio (o/e) 0.95, 90% interval 0.87 to 1.03. Synonymous variants: 141 observed, 155.57 expected, observed/expected ratio (o/e) 0.91, 90% interval 0.79 to 1.04.
Homologues: Orthologues: chimpanzee GOLM1 (99% identical), macaque GOLM1 (96% identical), dog GOLM1 (82% identical), pig GOLM1 (77% identical), guinea pig GOLM1 (74% identical), rat Golm1 (66% identical), mouse Golm1 (64% identical), rabbit GOLM1 (64% identical), tropical clawed frog golm1 (36% identical), zebrafish golm1 (24% identical). Paralogues in human: GOLM2 (26% identical).
Diseases named in the same sentence as GOLM1 in open-access papers:
GOLM1 is named in the same sentence as 127 diseases in open-access papers, as found by Europe PMC text mining. Sharing a sentence is not in itself a finding about the gene and the disease. The quoted sentences say what the papers report.
hepatocellular carcinoma (92 papers, 2008 to 2026). A malignant tumor that arises from hepatocytes. "GOLM1 is a Golgi-associated protein that functions, in part, as a chaperone for protein trafficking and has been shown in hepatocellular carcinoma to positively regulate PD-L1 production." (PMID 38889047, 2024). "Overexpression of Golgi membrane protein 1 (GOLM1) is closely associated with hepatocellular carcinoma (HCC) vascular invasion." (PMID 36211823, 2022). "The newly identified tumour‐promoting gene GOLM1 is involved in multiple types of tumours, such as hepatocellular carcinoma, oesophageal carcinoma, lung cancer and others." (PMID 39470578, 2024). "Research on hepatocellular carcinoma has indicated that GOLM1 regulates EGFR/RTK recycling to encourage liver cancer cells to proliferate and spread." (PMID 39470578, 2024). "Golgi membrane protein 1 (GOLM1) is correlated to hepatocellular carcinoma (HCC) progression and metastasis." (PMID 34795203, 2021). "Deregulated GOLM1 functioned as an oncogene and correlated with poor prognosis in many types of cancers, such as hepatocellular carcinoma 12, 17, prostate cancer 18, gastric cancer 11, esophagus cancer 19 and so on." (PMID 34729117, 2021). "GOLM1 aggravates cell growth and metastasis in breast cancer, and aggressiveness in non-small-cell carcinoma and hepatocellular carcinoma." (PMID 32781986, 2020). "An increasing number of studies have also revealed GOLM1 as a promoter of proliferation, invasion, and migration in diverse human cancers, including hepatocellular carcinoma, prostate cancer, oesophageal cancer, gastric cancer, cutaneous melanoma." (PMID 29282077, 2017). "GOLM1 has been shown to be overexpressed in human PCa tissue, lung adenocarcinoma, and hepatocellular carcinoma." (PMID 25115396, 2014). "Golgi membrane protein 1 (GOLM1) has been reported to participate in modulating the immunosuppressive microenvironment and it has been implicated in the onset and progression of hepatocellular carcinoma, glioblastoma, and melanoma." (PMID 38997719, 2024). "A previous study reveals that overexpressed GOLM1 promotes PD-L1 transport into TAMs in hepatocellular carcinoma, aggravating CD8+ T cell suppression and promoting tumor progression, which is similar to our results on MRMGPS-based immune cell infiltration in PCa." (PMID 37122696, 2023). "In addition, GOLM1 protein was found at high levels in the serum of patients with hepatocellular carcinoma." (PMID 24243830, 2013). "Golgi membrane protein 1 (GOLM1) is a Golgi-resident type 2 transmembrane protein known to be overexpressed in several cancers, including hepatocellular carcinoma (HCC), as well as in viral infections." (PMID 35948172, 2022). "Additionally, GOLM1 is associated with surface membrane protein transport and recycling growth factor responsive receptor tyrosine kinase (RTK) and epidermal growth factor receptor (EGFR) proteins between the golgi and cell surface in hepatocellular carcinoma." (PMID 34680291, 2021). "Furthermore, GOLM1 has been identified as a serum marker for hepatocellular carcinoma." (PMID 29282077, 2017). "The cholesterol–mTORC1 axis regulated autophagy through Golgi membrane protein 1 (GOLM1) and by interacting with LC3 through an LC3-interacting region (LIR) in hepatocellular cancer cells." (PMID 37190124, 2023). "proved that GOLM1 played a key role in cell cycle and metastasis of hepatocellular carcinoma (HCC) cells, and may serve as a prognostic indicator and therapeutic target in HCC patients." (PMID 33869063, 2021). "Golgi phosphoprotein 73 (GP73), encoded by GOLM1, is a highly expressed factor in hepatocellular carcinoma (HCC) cells and has been regarded for several years as a remarkable serum biomarker for the diagnosis of HCC." (PMID 31591387, 2019).
hepatocellular carcinoma (continued). "According to the previous research, GOLM1 can move from the trans‐Golgi network into the cytosol, where it can affect the cell surfaces recycling of EGFR/RTK, which is known to be essential for the development of hepatocellular carcinoma." (PMID 39470578, 2024). "What’s more, GOLM1 also acts as a positive regulator of Programmed Cell Death Ligand 1 (PD-L1) expression via the EGFR/Signal Transducer and Activator Of Transcription 3 (STAT3) signaling pathway in the human hepatocellular carcinoma." (PMID 39190284, 2024). "CASC4 has a paralog, GOLM1 (GOLPH2, GP73), which is a driver of hepatocellular carcinoma through various pathways, including cholesterol-dependent recycling of members of the erythroblastic oncogene B (ERBB) family of RTKs, such as the epithelial growth factor receptor 1 (EGFR/ERBB1) and ERBB4." (PMID 38030811, 2024). "In a recent study of hepatocellular carcinoma (HCC), golgi membrane protein 1 (GOLM1) was shown as a key target of miR-382, HCC cells metastasis status was inhibited when GOLM1 is down-regulated in HCC cells." (PMID 33005184, 2020). "Elevated Golgi phosphoprotein 2 (GP73, also known as GOLPH2 or GOLM1) expression in serum and liver, which can be induced by viral infection and cytokine treatments, is intimately connected with liver disease, including acute hepatitis, cirrhosis and hepatocellular carcinoma (HCC)." (PMID 29097707, 2017). "GOLM1 expression is elevated in liver diseases, such as acute and autoimmune hepatitis, hepatitis B virus (HBV) and hepatitis C virus (HCV) infections, alcohol-related liver diseases, nonobese nonalcoholic fatty liver disease (NAFLD), and hepatocellular carcinoma (HCC)." (PMID 35948172, 2022).
liver disease (56 papers, 2011 to 2026). "GOLM1, moreover, has been reported to be associated with the development of liver diseases." (PMID 33854600, 2021). "Early studies have shown that increased GOLM1 expression in hepatocytes seems to be a general feature of advanced liver disease." (PMID 36499755, 2022). "Genes up-regulated in common in advanced human liver fibrosis and in Ezh1/2-KO mouse liver include biomarkers of liver disease (e.g. Golm1) and genes that play a fundamental role in liver fibrogenesis and HCC (e.g., Spp1/Osteopontin)." (PMID 32428001, 2020).
liver cancer (41 papers, 2008 to 2025). An epithelial or non-epithelial malignant neoplasm that arises from the liver. "Although GOLM1 has been previously regarded as a diagnostic marker of liver cancer, it is an independent prognostic factor for liver cancer." (PMID 35154287, 2022). "GOLM1 belongs to the Golgi-associated protein and is a crucial promoter of liver cancer growth and metastasis." (PMID 35154287, 2022). "Recent investigations have demonstrated an upregulation of GOLM1 expression in multiple cancer types, including liver cancer, lung cancer, and pancreatic cancer." (PMID 38608280, 2024). "recently demonstrated that cholesterol inhibits the autophagic degradation of receptor tyrosine kinases in human liver cancer cells by interfering with the function of GOLM1 (Golgi membrane protein 1)." (PMID 36176395, 2022). "Abnormal overexpression of GOLM1 correlates with many kinds of cancers and diseases, such as liver cancer and in prostate cancer tissue." (PMID 33649292, 2021). "One study revealed that GOLM1 acts as an oncogene promoting liver cancer by adjusting epidermal growth factor receptor/receptor tyrosine kinase (EGFR/RTK) cell-surface recycling." (PMID 33649292, 2021). "Levels of circulating liver cancer markers such as Afp, Golm1, and active Tgfβ were significantly increased in the S1a/ETP mice compared to the S1a/Ctrl mice." (PMID 33110211, 2020). "Importantly, we found significant upregulation of hepatic cancer marker transcripts, including Afp, Golm1, Tgfb, Gpc3, Villin, and Ki67." (PMID 33110211, 2020). "For cirrhosis compared with NAFLD, the most significantly upregulated genes were related to liver cancer (ITGA2, GOLM1) and inflammation (ITGA2), inflammasome activation (JAG1), and fibrosis (JAG1)." (PMID 40489530, 2025). "Golgi membrane protein 1 (GOLM1), as an oncogene, promoted the growth and metastasis of liver cancer by selectively binding with epidermal growth factor receptor (EGFR)." (PMID 38155974, 2023). "The critical golgi related gens, GOLPH2, GOLM1 and GP73, can also be the potential biomarkers in prostate cancer and liver cancer.GOLPH3 was also reported to be the potential biomarker in some kinds of cancers." (PMID 29534690, 2018).
prostate carcinoma (38 papers, 2008 to 2025). A carcinoma that arises from epithelial cells of the prostate gland. "In this regard, five mRNAs (CCND1, LMTK2, FN1, EZH2, and GOLM1) were included in a gene panel for prostate cancer diagnosis and reported as differentially expressed in a Chinese cohort of 281 patients using RT-qPCR from tissue samples." (PMID 39595075, 2024). "A combination of genes circulating mRNA signature (GOLM1, NKX3-1 and TRPM8) was able to identify high-risk prostate cancer cases (85% of sensitivity and 58% of specificity)." (PMID 37091783, 2023). "For prostate cancer, PSA, PCA3, GOLM1, and EN2 serve as valuable markers, highlighting diagnostic and prognostic potential." (PMID 38250812, 2023). "In the same line of evidence, GOLM1 stimulates prostate cancer migration and invasion by triggering the PI3K/AKT/mTOR signaling pathway." (PMID 35805075, 2022). "Simultaneously, the high expression of GOLM1 is associated with a variety of cancers, including prostate cancer, non-small cell lung carcinoma (NSCLC), and HCC, and GOLM1 has been considered an early diagnostic marker of HCC." (PMID 36499755, 2022). "Further, we discovered that GOLM1 expression was markedly upregulated in prostate cancer tissues according to data from GEPIA database." (PMID 32781986, 2020). "Taken together, LINC00992 promoted the tumorigenesis of prostate cancer through upregulating GOLM1 expression." (PMID 32781986, 2020). "miR-145-5p expression is consistently downregulated also in prostate cancer, and its ectopic expression in prostate cancer cells inhibits cancer cell migration and invasion by targeting GOLM-1 (Golgi membrane protein-1) mRNA23." (PMID 30622242, 2019). "Our past studies demonstrated that hexokinase-2 (HK2) and Golgi membrane protein 1 (GOLM1) were directly regulated by miR-143 and miR-145-5p in renal carcinoma and prostate cancer, respectively." (PMID 27072587, 2016). "The novel Golgi phosphoprotein 2 (GOLPH2), also known as Golgi protein 73 (GP73) and Golgi membrane protein 1 (GOLM1), has recently been described as a diagnostic marker in prostate cancer with similar characteristics as alpha-methylacyl CoA racemase." (PMID 20184749, 2010). "Furthermore, within the urine of prostate cancer patients, the presence of Golgi membrane protein 1 (GOLM1) immunoreactivity has been identified, suggesting its potential as a biomarker for clinically localized prostate cancer." (PMID 38250812, 2023). "The differential expression of MYO6 and GOLM1 in AA prostate cancer tissue suggests transport of RTK proteins and the resulting oncogenic activity of Akt might be a good target to treat the AA aggressive prostate cancer phenotype." (PMID 34680291, 2021). "Currently, we also revealed GOLM1 as upregulated in prostate cancer." (PMID 32781986, 2020). "In prostate cancer, GOLM1 has also been corroborated as tumor promoter." (PMID 32781986, 2020). "Interestingly, we found that only Golgi membrane protein 1 (GOLM1) was highly expressed in four prostate cancer cell lines relative to normal controls." (PMID 32781986, 2020). "Similarly, GOLM1 expression was much higher in prostate cancer tissue samples than in peri-tumor samples." (PMID 32781986, 2020). "In addition, the mRNA and protein levels of GOLM1 were overexpressed in prostate cancer cells in contrast to RWPE-1 cells." (PMID 32781986, 2020). "Besides, GOLM1 has been previously revealed as a prostate cancer facilitator and was metastasis-related in prostate tumor." (PMID 32781986, 2020). "Collectively, GOLM1 was required in LINC00992-regulated prostate cancer cellular processes." (PMID 32781986, 2020). "The overexpression of GOLM1 is reported in prostate cancer and lung adenocarcinoma." (PMID 31681566, 2019). "GOLM1 is overexpressed in androgen-responsive Leydig cell tumor and prostate cancer." (PMID 24243830, 2013). "Thus, we hypothesized that GOLM1 might act as the downstream of LINC00992/miR-3935 signaling in prostate cancer." (PMID 32781986, 2020).
prostate carcinoma (continued). "Our studies demonstrated that Golgi membrane protein 1 (GOLM1) and hexokinase-2 (HK2) were directly controlled by miR-143-3p and miR-145-5p in prostate cancer and renal cell carcinoma, respectively." (PMID 35327465, 2022). "Future work will involve determining if AA prostate cancer tissues exhibit progression and metastatic potential via activated Akt through RTK recycling mechanisms promoted by MYO6 and GOLM1." (PMID 34680291, 2021). "By using luciferase reporter assay we validated that CDH2 and Golm-1 are miR-145-5p target genes also in the Thymic Carcinoma cell lines TC1889, as already published, respectively, for gastric and prostate cancer." (PMID 28486946, 2017). "GOLPH2 (golgi phosphoprotein 2, GOLM1) has recently been proposed as a biomarker for hepatocellular and prostate cancer." (PMID 19014428, 2008). "GOLM1 promotes HCC, glioma and prostate cancer proliferation and growth through the regulation of the EGFR/PDGFRα/RTK signaling pathway, thus resulting in the activation of PI3K/AKT/mTOR signaling cascade and in the positive feedback loop, already described in the previous section." (PMID 35805075, 2022). "GOLM1 is overexpressed in HCC, lung cancer, prostate cancer and is a serum biomarker of HCC38–40." (PMID 34795203, 2021). "In prostate cancer tissues, MYO6 and GOLM1 are known to co-locate at the golgi." (PMID 34680291, 2021). "GOLM1, CD24, PSCA, and the gene fusion TMPRSS2-ERG were selected as overexpressed mRNAs in prostate cancer, whereas ANXA3 and SLC45A3 were selected as underexpressed mRNAs in prostate cancer for evaluation." (PMID 33172003, 2020).
liver fibrosis (26 papers, 2013 to 2025). "Experimental studies have shown that Golgi membrane protein 1 (GOLM1) is significantly upregulated in carbon tetrachloride (CCL4) induced mouse liver fibrosis, and GOML1 induces PD-L1 expression and promotes fibrosis by activating EGFR/AKT/STAT3 signaling pathway." (PMID 37275876, 2023).
viral infection (23 papers, 2008 to 2025). "The GOLM1 gene encodes a type II Golgi transmembrane protein, which is mainly synthesized in the rough endoplasmic reticulum, assists in processing proteins in the Golgi, and is responsive to viral infections." (PMID 32141510, 2020). "GOLM1, a Golgi membrane protein, is predominantly expressed in epithelial cells and exhibits increased expression levels in viral infections and malignant diseases." (PMID 39470578, 2024). "GOLM1, a Golgi membrane protein, is commonly produced in epithelial cells and its expression is upregulated under the influence of viral infection." (PMID 37251569, 2023). "GOLM1 is a membrane protein located on the Golgi apparatus, which is mainly expressed by cells of the epithelial lineage and upregulated by virus infection." (PMID 36499755, 2022). "Golgi membrane protein 1 (Golm1) is a protein with yet unknown function that has been shown to increase in viral infections." (PMID 34464420, 2021). "GOLM1, although there are currently no studies connecting this protein to the ocular surface, has been recently associated with viral infection and its associated immune response." (PMID 30976209, 2019). "Along with these proteins, several other viral infection induced proteins such as LGALS3BP, GOLM1, and LTA4H were also increased." (PMID 35958562, 2022).
breast carcinoma (14 papers, 2012 to 2024). "Overexpression of MMP-13 mediated by GOLM1, C1r and Leptin has been shown to increase tumour growth in breast cancer, cutaneous squamous cell carcinoma and pancreatic cancer." (PMID 35805035, 2022). "For instance, in prostate and breast cancers, GOLM1 works as an oncogene by inducing cancer cell growth, migration, and invasion, inhibiting cell apoptosis." (PMID 34943605, 2021). "Some studies demonstrated that golgi somal membrane protein 1 (GOLM1) promoted the proliferation and metastasis of breast cancer cells by regulating matrix metalloproteinase-13 (MMP13)." (PMID 35127514, 2021). "Results showed NR5A2, CREB1 and GOLM1 expression levels were significantly higher in tamoxifen-resistant breast cancer cells." (PMID 27809310, 2016). "GOLM1 could promote breast cancer cell aggressiveness by regulating matrix metalloproteinase-13 (MMP13)." (PMID 39190284, 2024). "In our study, WGCNA was carried out to evaluate the biological role of GOLM1 in breast cancer." (PMID 33869063, 2021). "To note, the protein–protein interaction network of PIK3R1, IL1R1, MMP11, GOLM1, and VAV3 altogether connected by EGFR merits further work to understand the mechanism and develop an ideal treatment strategy for invasive small tumor-size breast cancers." (PMID 39190284, 2024). "Moreover, our results demonstrated that LINC01977 may exert its biological effect by targeting miR-212-3p/GOLM1 axis, which broaden our insights into the post-transcriptional regulation mechanism and help provide a novel prognostic indicator and therapeutic target for patients with breast cancer." (PMID 33869063, 2021). "Finally, our findings indicated that LINC01977 could promote breast cancer progression and chemoresistance to DOX by targeting miR-212-3p/GOLM1 axis." (PMID 33869063, 2021).